PINK1 (PTEN induced kinase 1)
Diseases named in the same sentence as PINK1 in open-access papers (continued):
Sharing a sentence is not in itself a finding about the gene and the disease.
diabetic kidney disease (25 papers, 2017 to 2026). Progressive kidney disorder caused by vascular damage to the glomerular capillaries, in patients with diabetes mellitus. "In renal tubular cells of diabetic kidney disease, increased mitochondrial ROS and mitochondrial fragmentation were associated with reduced Pink1/Parkin-mediated mitophagy and enhanced apoptosis." (PMID 31382550, 2019). "A recent study using Drosophila models demonstrated that promoting mitochondrial dynamics by inhibiting the PINK1-PRKN pathway can relieve diabetic nephropathy." (PMID 41508092, 2026). "Different models of diabetic nephropathy report on low expression of PINK1 accompanied by increased mitochondrial fragmentation." (PMID 39681572, 2024). "Reductions in autophagic vesicle formation along with the downregulation of PINK1 and parkin expression have been demonstrated in diabetic kidney disease models on mice subjects." (PMID 36839892, 2023). "PTEN-induced serine/threonine kinase 1 (PINK1) is a core organizer of mitochondrial quality control; however, its function in diabetic kidney disease remains controversial." (PMID 37928264, 2023). "The physiological role of PINK1 in the major cells involved in diabetic kidney disease including proximal tubular cells and podocytes will also be summarized." (PMID 33546409, 2021). "MitoQ exerts beneficial effects on tubular injury in diabetic kidney disease via Nrf2/PINK1-mediated mitophagy." (PMID 34825063, 2021). "In diabetic nephropathy, Pink1 transcriptional activity is controlled by the antioxidant FOXO 1, which promotes mitophagy and protects injured podocytes under HG conditions." (PMID 31382550, 2019). "A recent study showed that the mitochondria-targeted antioxidant MitoQ ameliorated the tubular injury mediated by mitophagy in diabetic kidney disease via Nrf2/PINK1." (PMID 29621130, 2018). "Recently, a study showed reduced mRNA expression of MFN2, PARKIN, and PINK1 in patients with diabetic nephropathy, which corroborates with our observations." (PMID 29326655, 2017). "Similarly, UA has been shown to protect against diabetic kidney disease and hypoglycemia-induced heart injury by activating the PINK1/Parkin mitophagy pathway." (PMID 41374004, 2025). "Our results illustrated that CERS6-derived ceramide may aggravate interstitial fibrosis in diabetic kidney disease by regulating PINK1-mediated mitophagy." (PMID 37458434, 2023). "In conclusion, PINK1 plays a pivotal role in suppressing mitochondrial dysfunction and tubular cell necroptosis under high glucose conditions and exerts protective effects in diabetic kidney disease." (PMID 37928264, 2023). "Besides, the formula comprising Astragalus mongholicus Bunge and Panax notoginseng (Burkill) F.H. Chen protects the kidney from inflammatory damage in diabetic nephropathy, possibly by inhibiting mTOR and activating PINK1/Parkin signaling to promote autophagy." (PMID 35903668, 2022). "We found PINK1/Parkin-mediated mitophagy was inhibited in diabetic kidney disease." (PMID 36605399, 2022). "PINK1/parkin signaling were found to decrease mitochondrial ROS (mtROS) and inflammasome activation in renal tubular epithelial cells, and to ameliorate fatty acid-induced apoptosis in diabetic kidney disease." (PMID 34359852, 2021). "Collectively, these studies suggested that targeting PINK1 may offer a promising alternative for the treatment of diabetic kidney disease." (PMID 33546409, 2021). "Notably, METTL3 governed PINK1 m6A modification via YTHDF2, driving renal tubular epithelial cell apoptosis and mitophagy in Diabetic Kidney Disease (DKD) pathogenesis." (PMID 41142801, 2025). "The mechanisms involved have not been generally well studied except for PINK1-mediated mitophagy which plays a protective role in diabetic kidney disease." (PMID 35614934, 2022).
glioblastoma (25 papers, 2017 to 2026). The most malignant astrocytic tumor (WHO grade IV). "Inactivating mutations are observed in glioblastoma and other cancers, and the overexpression of Parkin and PINK1 in breast and glioma cells attenuates cellular proliferation." (PMID 38156294, 2023). "In this sense, it has been described that PINK1 deficiency reprogramed glucose metabolism through HIF1α to maintain cell proliferation and even cancer growth, especially in glioblastoma." (PMID 37047483, 2023). "Research has shown that PINK1 can work as a regulator of the Warburg effect and a negative regulator of glioblastoma growth, and the loss of PINK1 contributes to the Warburg effect through ROS-dependent stabilization of HIF1A." (PMID 33244455, 2020). "Furthermore, mitochondrial potential assays and immunofluorescence studies showed that compounds such as CBD and CBG led to mitochondrial membrane potential loss and reduced PINK1 expression, correlating with cytotoxic effects in glioblastoma cell lines." (PMID 40565152, 2025). "For instance, in glioblastoma, the loss or gain of PINK1 may contribute to mitochondrial dysfunction and altered mitophagy, affecting tumor progression." (PMID 40565152, 2025). "For example, increased PINK1 expression in liver, kidney, pancreatic and endometrial cancers was associated with improved overall survival, while breast, cervical, ovarian, lung, glioblastoma, and melanoma cancers were associated with a poor prognosis." (PMID 36830954, 2023). "These diverse roles suggest that PINK1’s oncogenic potential in glioblastoma could be linked to broader cellular signaling pathways beyond mitophagy, emphasizing the need for further investigations to determine its therapeutic relevance in glioblastoma and other cancers." (PMID 40565152, 2025). "This suggests that PINK1 is epigenetically silenced in glioblastoma, potentially impairing mitochondrial quality control and contributing to tumor progression." (PMID 40565152, 2025). "In proneural glioblastoma subtypes, high PINK1 expression correlates with poorer survival, suggesting a pro-oncogenic role in specific molecular contexts." (PMID 40565152, 2025). "Deletions or reduced expression of PINK1 have also been observed in multiple human brain tumors, including glioblastoma, and correlate with poor clinical prognosis." (PMID 41516242, 2025). "Emerging evidence highlights molecular targets like GPR55 and PINK1 as key players in glioblastoma progression." (PMID 40565152, 2025). "PINK1 reduces glioblastoma proliferation by controlling aerobic glycolysis, reducing ROS production, and regulating the Warburg effect; furthermore, PINK1 plays a pivotal role in mitophagy." (PMID 40535571, 2025). "Beyond glioblastoma, these insights reveal opportunities to explore PINK1 as a therapeutic target or biomarker in a broader range of cancers." (PMID 40565152, 2025). "Cannabichromene (CBC), cannabigerol (CBG), cannabidiol (CBD), and Piper nigrum derivates exhibited strong binding affinities relative to glioblastoma-associated targets GPR55 and PINK1." (PMID 40565152, 2025). "This context-dependent variability underscores the need for stratifying glioblastoma patients based on molecular profiles when considering PINK1-targeted therapies." (PMID 40565152, 2025). "These platforms revealed patterns mainly of PINK1 expression in glioblastoma tissues compared to normal brain samples." (PMID 40565152, 2025). "In addition, PINK1 could suppress the growth and invasion of cells, while loss of PINK1 resulted in the Warburg effect by promoting the elevation of hypoxia‐inducible factor‐1 and reactive oxygen species in glioblastoma." (PMID 37382962, 2023). "Other reports showed that PINK1 knockdown upregulated cell growth in glioblastoma, and that ectopic overexpression of PINK1 suppressed the colony formation ability of MCF7 cells in soft agar." (PMID 33888730, 2021).
glioblastoma (continued). "PINK1 (PARK6) a kinase involved in the regulation of autophagy and the cell cycle, has been involved in glioblastoma, and ovarian cancers." (PMID 29255414, 2017). "Additionally, Kaplan–Meier survival analysis in glioma indicates that lower PINK1 levels correlate with better overall survival, further supporting its potential oncogenic role in glioblastoma and highlighting the need for functional validation." (PMID 40565152, 2025). "This drastic reduction in expression may indicate a crucial role of PINK1 in glioblastoma biology (as a potential indicator of tumor progression)." (PMID 40565152, 2025). "Furthermore, transcriptomic and survival data from public databases underscored the potential of PINK1 as a critical biomarker in glioblastoma." (PMID 40565152, 2025). "However, in glioblastoma samples, PINK1 was present in positive cases, suggesting a tumor-specific role." (PMID 40565152, 2025). "Nevertheless, PINK1 antagonizes cell growth and the Warburg effect in glioblastoma." (PMID 30595797, 2018). "Indeed, inhibition of HK2 by ketoconazole and posaconazole revealed an inhibitory effect on GBM both in vitro and in vivo; activation of PINK1 suppresses ROS and tumor growth through FOXO3a and reduces in vivo glioblastoma growth in orthotopic mouse xenograft models." (PMID 35453557, 2022). "In the context of tumorigenicity, mutations and deletions of key mitophagy molecular components PINK1 (PARK6) and Parkin (PARK2) genes are frequently observed in various cancer types, including bladder, breast, lung, ovarian, colon, and glioblastoma." (PMID 39201332, 2024). "This figure compares the expression of PINK1 and GPR55 in glioblastoma tumor tissues versus a non-tumoral human cortex, highlighting their potential associations with glioblastoma characteristics." (PMID 40565152, 2025). "Our IHC results revealed that PINK1 was present in neurons and endothelial cells but absent in normal glia, whereas in glioblastoma samples, positive cases (65%) exhibited PINK1 expression." (PMID 40565152, 2025). "Additionally, immunohistochemical (IHC) analyses of PINK1 and GPR55 were performed on glioblastoma samples from Colombian patients, providing insights into their expression patterns in tumor tissues." (PMID 40565152, 2025). "As in cardiomyocytes, 15NG decreased HK-II in the mitochondrial fraction isolated from the 1321N1 human glioblastoma cell line and induced an increase in mitochondrial Parkin but not PINK1 levels, while FCCP treatment increased both Parkin and PINK1." (PMID 31570704, 2019).
ovarian carcinoma (25 papers, 2017 to 2025). A malignant neoplasm originating from the surface ovarian epithelium. "Our analysis revealed that a high expression of PINK1 was significantly associated with a worse prognosis in patients with ovarian cancer." (PMID 37940999, 2023). "PINK1 was strongly associated with a poor prognosis in ovarian cancer patients and promoted metastasis and chemoresistance in ovarian cancer cells." (PMID 37940999, 2023). "The results suggested that the association between PINK1 and poor prognosis of ovarian cancer was more stable and convincing, so PINK1 was chosen for further research." (PMID 37940999, 2023). "However, in the case of lung, esophageal, and ovarian cancers, low PINK1 expression was associated with a better overall survival rate." (PMID 36830954, 2023). "The results showed an increased LC3II/LC3I ratio, PINK1 and Parkin expression in the group treated with ovarian cancer cell-derived EVs when compared to that treated with normal ovarian cell-derived EVs." (PMID 38468343, 2024). "PINK1/Parkin-mediated mitophagy has been proposed to be the main mechanism of cisplatin resistance in ovarian cancer cells." (PMID 39668821, 2024). "PINK1 was observed to increase AKT activity in ovarian cancer cells as well and enhanced resistance to chemotherapy." (PMID 39440945, 2024). "In our experimental setting, we demonstrated that, in ovarian cancer, PINK1 played a critical role in promoting metastasis and chemotherapy resistance." (PMID 37940999, 2023). "Western blot analysis demonstrated a significant increase in PINK1 protein expression in SKOV3/DDP cells, which suggests the association of PINK1 with cisplatin resistance in ovarian cancer." (PMID 37940999, 2023). "Collectively, these results provide strong evidence supporting the notion that PINK1 promotes ovarian cancer metastasis through its kinase activity." (PMID 37940999, 2023). "The potential correlation between PINK1 and the tendency for ovarian cancer metastasis warrants further investigation." (PMID 37940999, 2023). "PINK1 promotes ovarian cancer metastasis and chemotherapy resistance through the regulation of PTEN." (PMID 37940999, 2023). "The collective findings reveal that PINK1 plays a significant role in the metastasis and unfavorable prognosis of ovarian cancer." (PMID 37940999, 2023). "Our study suggests that PINK1 contributes to ovarian cancer metastasis and chemotherapy resistance through the regulation of PTEN via a non-canonical pathway." (PMID 37940999, 2023). "This study revealed that phosphorylation of PTEN at Ser179 by PINK1 prevented nuclear import, thus promoting ovarian cancer metastasis and cisplatin resistance." (PMID 37940999, 2023). "In principle, these data argue a prominent role of PINK1 in mediating metastasis and chemoresistance of ovarian cancer." (PMID 37940999, 2023). "Meta-analysis was conducted to depict the results of the relativity between PINK1 expression and ovarian cancer prognosis." (PMID 37940999, 2023). "Following the overexpression or knockdown of PINK1, we carried out nucleoplasmic separation on ovarian cancer cells." (PMID 37940999, 2023). "Then, we evaluated the effect of PINK1 on the proliferative ability of ovarian cancer cells using EdU and CCK-8 assays." (PMID 37940999, 2023). "A recent meta-analysis conducted on individuals with ovarian cancer found a strong correlation between elevated PINK1 mRNA levels and unfavorable prognosis." (PMID 37940999, 2023). "Although the canonical PINK1/PRKN (parkin RBR E3 ubiquitin protein ligase) pathway showed weak effects in ovarian cancer, PINK1 was identified to interact with PTEN and phosphorylate it at Serine179." (PMID 37940999, 2023). "Consistent with our local cohort data, these results point to PINK1 overexpression as an unfavorable indicator for ovarian cancer." (PMID 37940999, 2023).
ovarian carcinoma (continued). "To confirm these results, we used human SK-OV-3 ovarian cancer cells that we have identified as a robust system to study endogenous PINK1-Parkin signalling." (PMID 35042401, 2022). "The results showed that PINK1 expression was lower in several cancer groups than in normal tissues, including brain, breast, colorectal, esophageal, head and neck, liver and ovarian cancers as well as leukemia and melanoma." (PMID 33244455, 2020). "According to our study, we found that PINK1 expression was lower in several cancers, including brain, breast, colorectal, esophageal, head and neck, liver, and ovarian cancers as well as leukemia and melanoma, at the mRNA level." (PMID 33244455, 2020). "The mitochondrial autophagy-associated PINK1/parkin pathway, BNIP3 molecules, and mitochondrial Ca2+ absorption promotion in the MAM might all be used to manipulate ovarian cancer cell metastasis and drug resistance." (PMID 38711526, 2024). "This suggests that PINK1 may play an important role in the specific metastasis process of ovarian cancer to the omentum." (PMID 37940999, 2023). "Our results also encourage the relevance of PINK1 expression levels with ovarian cancer prognosis." (PMID 37940999, 2023). "Therefore, our current study proposes new insights into a novel mechanism of ovarian cancer metastasis and chemotherapy resistance, and provides a theoretical basis of possible clinical treatment through PINK1 inhibition." (PMID 37940999, 2023). "We next investigated whether the canonical PINK1/Parkin pathway played a role in ovarian cancer development and chemoresistance, but low levels of Parkin in ovarian cancer were observed via sample data retrieved from The Human Protein Atlas." (PMID 37940999, 2023). "We next evaluated whether the kinase activity of PINK1 is necessary for its effect on ovarian cancer metastasis by over-expressing a PINK1 kinase inactive mutant plasmid in A2780 cells." (PMID 37940999, 2023). "The population intervention of PINK1 in the future may be a valuable approach for prevention and treatment of ovarian cancer." (PMID 37940999, 2023). "In summary, inhibition of PINK1 by potential drug may be a promising candidate for ovarian cancer treatment." (PMID 37940999, 2023). "The results showed that the high expression level of PINK1 was significantly associated with the worse prognosis in ovarian cancer patients, while the WIPI1 expression level was not significant related to the poor prognosis." (PMID 37940999, 2023). "In addition, our results revealed that Parkin expression level was extremely low in ovarian cancer, indicating that PINK1 regulates other substrates to promote ovarian cancer metastasis and chemoresistance." (PMID 37940999, 2023). "Considering the comparable HR value of PINK1 and WIPI1, we used Kaplan–Meier Plotter database to further evaluate the association between PINK1 (or WIPI1) expression level and overall survival in patients with ovarian cancer." (PMID 37940999, 2023). "Given that poor prognosis of ovarian cancer is often associated with metastasis, and high PINK1 expression was found to be correlated with greater omentum metastasis, we went ahead to assess PINK1 protein levels within primary and metastatic ovarian cancer tissues." (PMID 37940999, 2023). "Given the important role of epithelial-mesenchymal transition (EMT) in tumor metastasis, we investigated whether PINK1 could promote EMT in ovarian cancer cells." (PMID 37940999, 2023). "Therefore, these two particular cell lines were selected to determine the impact of PINK1 on ovarian cancer." (PMID 37940999, 2023). "Moreover, the protein level of p-AKT was higher in human ovarian cancer metastases tissues compared to primary tumors, consistent with the expression level of PINK1." (PMID 37940999, 2023).